XKR3 (XK related 3)
Synonyms: XRG3; MGC57211; XTES
Tractability: Antibody: UniProt places it where antibodies can reach, with high confidence; UniProt predicts a signal peptide or a membrane-spanning region; its Gene Ontology location is reachable by antibodies, with medium confidence.
Gene: Protein-coding gene on chromosome 22 (16,783,412 to 16,825,411, reverse strand). Ensembl gene ENSG00000172967.
Subcellular location: Cell membrane
Gene Ontology:
Cellular component: membrane; plasma membrane
Genetic constraint (gnomAD): Loss-of-function variants: 26 observed, 40.99 expected, observed/expected ratio (o/e) 0.63, 90% interval 0.46 to 0.88. The upper end of that interval is the gene's LOEUF score, 0.88, which puts it in group 3 of 6, group 1 being the genes least tolerant of losing a copy. Missense variants: 448 observed, 546.09 expected, observed/expected ratio (o/e) 0.82, 90% interval 0.76 to 0.89. Synonymous variants: 190 observed, 199.42 expected, observed/expected ratio (o/e) 0.95, 90% interval 0.85 to 1.08.
Homologues: Orthologues: chimpanzee XKR3 (95% identical), macaque XKR3 (78% identical), tropical clawed frog xkrx (37% identical), zebrafish xkrx (34% identical). Paralogues in human: XKRX (46% identical), XK (32% identical).
Diseases named in the same sentence as XKR3 in open-access papers:
XKR3 is named in the same sentence as 4 diseases in open-access papers, as found by Europe PMC text mining. Sharing a sentence is not in itself a finding about the gene and the disease. The quoted sentences say what the papers report.
pneumonia (1 paper, 2014). An acute, acute and chronic, or chronic inflammation focally or diffusely affecting the lung parenchyma, caused by an infection in one or both of the lungs (by bacteria, viruses, fungi, or mycoplasma.). "rs9605146 in the XKR3 gene is associated with increased susceptibility in the ARDS population and all subgroups except the African American with sepsis etiology group and the African American with pneumonia etiology group when analyzed individually." (PMID 25372662, 2014).
XKR3 also shares sentences with these, for which no sentence is quoted: aneurysm (1 paper); leukemia (1); Sepsis (1).